KMT2A (lysine methyltransferase 2A)
Diseases named in the same sentence as KMT2A in open-access papers (continued):
Sharing a sentence is not in itself a finding about the gene and the disease.
leukemia (continued). "This led to a downregulation of KMT2A-fusion targets, differentiation of leukemic blasts, and prolonged survival of mouse models of KMT2A-rearranged leukemia." (PMID 31555628, 2019). "Loss-of-function mouse models, as well as small molecular inhibitors of DOT1L, reported that KMT2A-rearranged leukemias are DOT1L dependent for proliferation." (PMID 31555628, 2019). "Leukemias driven by chromosomal translocation of the mixed-lineage leukemia gene (MLL or KMT2A) are highly prevalent in pediatric oncology." (PMID 31157223, 2019). "Leukaemia harbouring rearrangements of the KMT2A gene (formerly known as MLL/mixed‐lineage leukaemia and also known as HRX or TRX1) represent a unique subtype of acute leukaemia, characterised by a rapid and aggressive onset with generally poor prognosis." (PMID 32721124, 2019). "In contrast to its role in HPT-JT, our work and others revealed a requisite role for the PAF1c complex in leukemias harboring a MLL (KMT2a) translocation." (PMID 29774127, 2018). "For example, in spite of the fact that six partners of KMT2A gene account for majority KMT2A-rearranged leukemia, more than 135 partners of KMT2A have been identified so far." (PMID 29688850, 2018). "The MLL/KMT2A gene was one of the first epigenetic regulators known to be involved in leukemia pathogenesis." (PMID 29527516, 2018). "It is believed that some of the disruptions appear during fetal development especially in the case of childhood leukemia with rearrangements of the KMT2A (MLL1) gene and ALL with TEL-AML1(ETV6-RUNX1) translocation." (PMID 29642462, 2018). "Genetic rearrangements involving KMT2A gene are frequently involved in lymphoid, myeloid and mixed lineage leukemia." (PMID 28535805, 2017). "KMT2A rearrangements account for approximately 10% of human leukemias, and more than 70 fusion proteins have been identified." (PMID 28968975, 2017). "Pediatric AMLs with mixed lineage leukemia (MLL) rearrangements (or KMT2A, lysine (K)-specific methyltransferase 2A) represent about 20% of all pediatric AML patients." (PMID 27351222, 2016). "MLL-r leukemia is characterized by a reciprocal translocation involving the MLL gene located on chromosome 11q23 (also known as KMT2A, HRX, HTRX1 or ALL1), that encodes the MLL1 protein." (PMID 27317766, 2016). "Infant leukemias are a subgroup with frequent MLL (KMT2A) rearrangements, FLT3 overexpression and high sensitivity to cytarabine, but dismal prognosis." (PMID 27391351, 2016). "Therefore, this combination has been addressed in various preclinical studies: First, BCL2 itself is an important target gene of the KMT2A‐fusion and a critical dependency KMT2A‐rearranged leukemia." (PMID 39887730, 2026). "Consequently, by recruitment of DOT1L as well as the SEC via different mechanisms, KMT2A‐fusion proteins can modify chromatin architecture and directly drive transcriptional elongation at KMT2A‐target genes for the initiation and maintenance of leukemia." (PMID 39887730, 2026). "However, when KMT2A is disrupted or altered by chromosomal translocations, it leads to the formation of fusion proteins that drive the development of leukemia by hijacking normal cellular mechanisms and altering gene expression profiles." (PMID 40374809, 2025). "Is there any molecular mechanistic overlap between MECOM and KMT2A rearranged leukemia?" (PMID 40255434, 2025). "To explore our hypothesis that, like pediatric leukemia, unknown gene fusions might be present in KMT2A-rearranged adult AML, we performed transcriptome-wide surveillance for fusion genes using RNA sequencing (RNA-seq)." (PMID 39823827, 2025). "Since AF4 is one of the partner genes for KMT2A, could therapeutic approaches currently utilized or studied for leukemia with KMT2 rearrangement be applicable to those with MECOM rearrangement?" (PMID 40255434, 2025).
leukemia (continued). "Infant KMT2A-rearranged leukemias are a paradigmatic model of such interactions: most arise prenatally, are driven by KMT2A fusion proteins that reprogramme HOX-dependent transcription, and may be modulated by in utero and early-life environmental exposures." (PMID 41514520, 2025). "Several fusion proteins are described in acute leukemia, mainly with other epigenetic or transcriptional regulators like AFF1, MLLT1, or MLLT3, accounting for strongly divergent epigenomic, and gene expression patterns in KMT2A‐rearranged (KMT2A‐r) leukemia compared to other cytogenetic entities." (PMID 39754404, 2025). "Targeted inhibitors: Efforts to optimize CDK4/CDK6 blockade (e.g., combination regimens or PROTACs), PI3K/AKT/mTOR inhibition (rapalogues in trials), BH3 mimetics such as venetoclax, and menin inhibitors for KMT2A-rearranged leukemias, several of which have shown promising clinical activity." (PMID 41009342, 2025). "Recent preclinical studies have demonstrated that peptidomimetic and small-molecule inhibitors disrupting the KMT2A/WDR5 interaction could serve as potential therapies for KMT2A-r leukemia." (PMID 40361241, 2025). "Regarding future treatment strategies, menin inhibitors such as revumenib, which is currently used for the treatment of KMT2A-rearranged leukemias, may be a potential option." (PMID 41153634, 2025). "Another possibility is that the leukemia initiating cell may provide a unique and distinct epigenetic landscape for KMT2A::AFF1 binding, driving differential enhancer usage." (PMID 40729681, 2025). "This review aims to provide a comprehensive overview of the molecular characteristics, prognostic implications, and emerging targeted therapies for KMT2A-rearranged AML, highlighting recent advances that lead the way toward precision medicine in this high-risk leukemia subtype." (PMID 40361241, 2025). "Moreover, driver genes, as RAS, FLT3, NPM1, EVI1 and KMT2A shape the interaction between polyamine metabolic pathway and leukemia-supporting functions, resulting in selective vulnerabilities, as unveiled by drugs targeting PRMT5." (PMID 40603833, 2025). "A recent report indicates that the chromatin adapter protein Menin might serve as a reader for H3K79me2, potentially explaining the importance of this mark for leukemias driven by Menin-KMT2A complexes." (PMID 40781484, 2025). "The KMT2A gene, once termed a mixed-lineage leukemia (MLL) gene, is well known for its promiscuity, as it fuses with over 100 partner genes with numerous breakpoints in the context of hematological malignancies, giving rise to challenges in detection with conventional diagnostic methods." (PMID 39682241, 2024). "HOXA9 transcription is dependent on DOT1L-mediated H3K79 methylation in KMT2A-r leukemia." (PMID 38601080, 2024). "Moreover, while the blockage of HOXA9, an KMT2A downstream target, sensitizes KMT2A‐r leukemia to PARP inhibitors and impairs DDR, the overexpression of HOXA9 rather confers PARP inhibitor resistance to AML1‐ETO and PML‐RARα transformed cells." (PMID 39428967, 2024). "Additionally, targeting MYC, a key oncogene frequently upregulated in KMT2A-rearranged leukemia, offers another approach." (PMID 39682203, 2024). "Thus, for KMT2A‐r leukemias, one possible treatment approach is to hinder the Menin‐KMT2A interaction." (PMID 39428967, 2024). "The KMT2A fusion targets vary among leukemia lineage subtypes." (PMID 39303915, 2024). "By inhibiting the menin–KMT2A interaction, menin inhibitors reduce the chromatin binding and oncogenic effects of NPM1c, leading to decreased transcription of leukemia-promoting genes, ultimately promoting differentiation and reducing leukemic cell proliferation." (PMID 39682203, 2024). "There are almost 120 known fusion partners of KMT2A reported in infant leukaemia previously." (PMID 39463522, 2024).
leukemia (continued). "When genetic aberrations occur in genes that govern cell plasticity and differentiation, namely KMT2A, the resultant leukemia cell may have complex immunophenotypes and transcriptional states resembling the earliest precursor cells." (PMID 39303915, 2024). "After the breakthrough discovery of oncogenic f-circRNAs in leukemia with KMT2A::MLLT3 (MLL::AF9), followed by the finding of f-circRNAs in other malignancies with different translocations, no data emerged about chimeric circRNAs in leukemias with other rearrangements involving the KMT2A gene." (PMID 36585787, 2023). "In the Japanese Pediatric Leukemia/Lymphoma Study Group trial MLL-10, by introducing intensive chemotherapy, the indication of HSCT was restricted to patients with high-risk (HR) features only (KMT2A-r and either age <180 days or the presence of central nervous system leukemia)." (PMID 36979800, 2023). "KMT2A-rearrangements are not only restricted to leukemia of myeloid lineage." (PMID 38174649, 2023). "Therefore, accumulating evidence has demonstrated that inhibition of the high-affinity relationship between menin and mixed-lineage leukemia 1 (MLL1 and KMT2A) is an effective treatment for MLL-rearranged (MLL-r) leukemia in vitro and in vivo." (PMID 37049787, 2023). "We conclude that the role of MEN1 in leukemia is not limited to its interaction with KMT2A, hence pharmacological degradation may be a better approach than the inhibition of individual MEN1 PPIs." (PMID 38003662, 2023). "Rearrangements in KMT2A, NUP98 and mutated NPM1 are considered potent drivers of leukemia but may be accompanied by activation of other oncogenic pathways of both prognostic and therapeutic relevance." (PMID 38174649, 2023). "Besides, in AML with mutated NPM1, the KMT2A-menin synergy prompts HOX and MEIS1-mediated transcription of leukemia associated genes." (PMID 37816719, 2023). "VTP50469 was the first small-molecule inhibitor of the menin-KMT2A interaction; treatment of KMT2A-rearranged leukemia cell lines and primary samples with this agent led to downregulation of the classic KMT2A gene signature and prolonged survival (even cures) in mice." (PMID 38137469, 2023). "Although the duplication of KMT2A is a rare molecular event in childhood leukemia, multiple case reports showed that patients with KMT2A::MLLT10 duplication remained in first complete remission with negative minimal residual disease at 3.5 years from diagnosis." (PMID 37942413, 2023). "Interestingly, gene expression programs driven by oncogenic KMT2A-fusions are also relevant for other subtypes of leukemia, especially NPM1-mutant (NPM1c) AML." (PMID 38049829, 2023). "As the presence of the KMT2A-fusion may create secondary dependencies, we aimed to explore the proteomic landscape of KMT2A-r leukemia." (PMID 38049829, 2023). "While one study classifies this mutation as a poor prognostic factor, the other ones present no significant impact on the clinical outcome or prognostic features, and still others indicate the synergizing effect of PI3K-RAS with KMT2A rearrangements that reduces leukemia latency." (PMID 36979800, 2023). "Early in the definition of MPAL, chromosomal anomalies also encountered in some cases of acute myeloid (AML) or acute lymphoblastic (ALL) leukemia were recognized defining specific entities: MPAL with BCR-ABL1 and MPAL with KMT2A (formerly the MLL mixed lineage leukemia gene) rearrangements." (PMID 35380407, 2022). "KMT2A was shown to be a dominant cancer gene affected by recurrent translocations in leukemias." (PMID 35058979, 2022). "Because KMT2A is a promiscuous gene and the distribution of fusion partners varies according to leukemia subtypes, we hypothesized that SKIDA1 and LAMP5 expression could be associated with specific gene rearrangements." (PMID 35734412, 2022).
leukemia (continued). "With respect to this tumorigenic role, however, our result should be interpreted with caution; gain-of-function mechanisms that are likely not captured by our analysis are probably also involved, as evidenced from KMT2A translocations that act as drivers in certain types of leukemias." (PMID 35727845, 2022). "KMT2A exerts its function by forming a core-complex with other proteins; for this reason, the inhibition of KMT2A with its interaction partners, both histone and non-histone proteins, is a promising pharmacological strategy when KMT2A rearrangements are drivers of pathology, such as in leukemia." (PMID 35328068, 2022). "KMT2A-rearranged infant ALL is an aggressive childhood leukemia with poor prognosis." (PMID 35288693, 2022). "Among the TFs that we and others identified to be selectively essential and overexpressed in KMT2A-rearranged leukemia, MEF2C, RUNX2, and MEIS1 are well-established direct targets of KMT2A fusion oncoproteins, prompting us to consider that one of these TFs drives IRF8 overexpression." (PMID 35301220, 2022). "KMT2A fusions account for 78% of fusions in leukemia and the frequencies of different forms vary from 0.05 to 35%, suggesting that KMT2A fusions may be an important driver of leukemia." (PMID 35945623, 2022). "Based on whole-genome sequencing (WGS) and whole-exome sequencing studies, it was suggested that KMT2A rearrangement alone may be sufficient for inducing leukemia in some cases due to the harboring of very few cooperating lesions." (PMID 35269896, 2022). "Accordingly, many of the studies focused on KMT2A-rearranged leukemia, the most translocated genes in infant leukemia, demonstrated that expression of KMT2A-MLLT3 in fetal liver-derived HSPC gives rise to a leukemic phenotype often expressing lymphoid surface markers." (PMID 35159287, 2022). "In the current study, to identify new potential molecular mechanisms characterizing KMT2A/AFF1+ B-ALL, we investigated, for the first time, the case of monozygotic twins with the discordant diagnosis of KMT2A/AFF1 leukemia by exploiting different “-omics” approaches." (PMID 34575904, 2021). "In the case of KMT2Ar leukemias, KMT2A will also represent KMT2A-FP activity." (PMID 34088716, 2021). "Rearrangements of the mixed-lineage leukemia 1 (MLL1) gene (now renamed Lysine [K]-specific methyl transferase 2A or KMT2A) on chromosome 11q23 to over 80 different partner genes define a subtype of leukemia with lymphoid and myeloid features and poor prognosis." (PMID 34501239, 2021). "When overexpressed in murine hematopoietic progenitors, MN1 causes an aggressive AML characterized by an aberrant myeloid precursor-like gene expression program that shares features of KMT2A-rearranged (KMT2A-r) leukemia, including high levels of Hoxa and Meis1 gene expression." (PMID 33542482, 2021). "Compounds that target a critical KMT2A–Menin interaction have proven effective in KMT2A-r leukemia." (PMID 33542482, 2021). "Our finding that SID7969543 also targets CALM-AF10 translocated leukemia cells, supports previous reports showing that KMT2A and CALM-AF10 translocations rely on common underlying leukemogenic pathways and further emphasizes that both leukemia subtypes share common targetable vulnerabilities." (PMID 35127484, 2021). "We then compared oncoprotein target sites among leukemias with different KMT2A fusions." (PMID 34663924, 2021). "However, BAL with lysine methyltransferase 2A (KMT2A, previously called Mixed lineage leukaemia, MLL) gene rearrangement (KMT2Ar, previously called MLLr) is rare." (PMID 34330316, 2021). "The results will hopefully clarify the utility of blinatumomab in these patients, and also regarding the lineage switch with the outgrowth of myeloid leukemia that several groups have described for KMT2A-rearranged leukemias under the selective pressure of blinatumomab." (PMID 34201368, 2021).
leukemia (continued). "Indeed, pharmacologic inhibition of the Menin/Kmt2a interaction decreased colony formation and leukemia burden in models of murine and human MN1-driven AML in vivo and in vitro, respectively." (PMID 33542482, 2021). "These groups of divergent KMT2A fusion oncoprotein targets may contribute to the phenotypic plasticity of KMT2Ar leukemias." (PMID 34663924, 2021). "KMT2A gene rearrangements in leukemias have been studied for the longest time." (PMID 33302406, 2020). "Notably, both the non-rearranged allele of Kmt2a and Mllt1 as well as the reciprocal product Mllt1-Kmt2a fusion were also expressed in the leukemia cells." (PMID 33134860, 2020). "However, the aberrant recruitment of DOT1L by a majority of KMT2A-fusion partners results in an inappropriate hypermethylation and overexpression of downstream, targeted genes that promote leukemia." (PMID 32050659, 2020). "The first family member to be linked to cancer development was KMT2A (MLL1), for which translocations resulting in oncogenic fusion proteins were first discovered in leukemias, and non-synonymous mutations, predominantly frameshift and nonsense, are frequently found in several solid tumor types." (PMID 32471474, 2020). "Because KMT2A-PTD alone does not generate leukemia, the acquisition of other cooperating mutations is required for leukemia transformation." (PMID 32015320, 2020). "Finally, another menin-KMT2A inhibitor, Kura Oncology (KO)-539, has been shown to inhibit leukemia growth and prolong survival in KMT2A-rearranged cell lines and in vivo models, earning the FDA Orphan Drug Designation." (PMID 32050659, 2020). "For instance, the RNA binding protein MBNL1 is overexpressed in KMT2A (MLL) rearranged leukemias." (PMID 32784800, 2020). "MLL fusion leukemia is an aggressive leukemia carrying chimeric fusion of the MLL (KMT2A) gene." (PMID 31160638, 2019). "Notably, MENIN PPI inhibitors were shown to have potent anti-cancer activity not only in KMT2A fusion-driven leukemia but also in prostate tumors." (PMID 31681706, 2019). "Limited studies have addressed the contribution of Ptpn11 to KMT2A-driven leukemia in vivo." (PMID 31723831, 2019). "In MLL leukemias, the KMT2A gene is disrupted ensuing chromosomal translocation." (PMID 31195686, 2019). "Moreover, chromatin modifiers are already recognized as a cancer therapy target and clinical trials for the treatment of MLL1/KMT2A-fusion leukemia provide evidence for the development of drugs targeting the members of KMT2 family." (PMID 30093974, 2018). "A therapeutic potential and antileukemic activity was recently demonstrated in a study of the MM-401 compound targeting MLL1/KMT2A H3K4 methyltransferase activity in mixed lineage leukemia, suggesting that wild type MLL1 is necessary for MLL1-rearrangement driven leukemia." (PMID 28054944, 2017). "KMT2A, a myeloid/mixed lymphoid leukemia gene, is a histone H3 lysine 4-specific methyltransferase." (PMID 26208029, 2015). "Interestingly, in KMT2A::MLLT3 rearranged MOLM13 cells the same analysis revealed predominant binding of DOT1L to promoter regions and no relevant association with putative enhancers indicating a function in MPN cells that is distinct from KMT2A-rearranged leukemia." (PMID 40781484, 2025). "Identification of the KMT2A::MLLT3 fusion transcript indicated malignancy-associated HLH in the setting of evolving leukemia, even though the diagnosis of leukemia could not be made at that point." (PMID 40094975, 2025). "Additionally, we showed that a TCR targeting KMT2A::AFF1 could contribute to leukemia control in vivo against the autologous tumor." (PMID 40707674, 2025). "Understanding whether the H3K4 trimethylation activity of KMT2B is disturbed in KMT2A-rearranged leukemia, and particularly in context with KMT2A::AFF1 and KMT2A::MLLT3 fusion genes, represents an intriguing next chapter in illuminating the pathobiology of KMT2A-rearranged leukemia." (PMID 39834944, 2024).